ELN (elastin)
Diseases named in the same sentence as ELN in open-access papers (continued):
Sharing a sentence is not in itself a finding about the gene and the disease.
skin aging (36 papers, 2014 to 2025). The gradual irreversible changes in structure of skin that occur as a result of the passage of time.. "Changes in collagen and elastin in the extracellular matrix (ECM) are primary causes of clinical manifestations of skin aging, such as wrinkles, sagging, and laxity." (PMID 40115263, 2025). "This process promotes collagen and elastin synthesis, augments the content of collagen fibers and elastic fibers in the dermis, and improves signs associated with skin aging." (PMID 40969599, 2025). "ROS can damage DNA and RNA, resulting in reduced translation efficiency and adenosine triphosphate (ATP) synthesis, which in turn causes abnormal collagen and elastin synthesis, eventually leading to skin aging." (PMID 36364921, 2022). "These provide beneficial characteristics of EVs associated with TGFβ stimulation in the correction of skin aging by elastin production." (PMID 36009357, 2022). "Skin aging is generally caused by a decline in the components of the extracellular matrix (e.g., collagen and elastin) and due to inflammatory phenomena." (PMID 31509972, 2019). "Indeed, it is known that reactive oxygen species (ROS), generated by several environmental factors causing skin aging, can lead to the degradation of important components of the dermal extracellular matrix such as collagens and elastin." (PMID 34573004, 2021). "During aging, elastase activity increases, leading to the enhanced degradation of dermal elastin, which contribute to reduced skin elasticity and visible signs of skin aging." (PMID 40722908, 2025). "These processes promote collagen degradation, elastin fragmentation, lipid peroxidation, and disruption of the dermal extracellular matrix—hallmarks of extrinsic skin aging." (PMID 41598216, 2025). "The reduction in collagen and elastin in the dermis layer is one of the signs of skin aging outcomes." (PMID 40006016, 2025). "Wrinkles, loss of elasticity, hyperpigmentation, and dryness are classical symptoms of skin aging, mainly due to the activity of key enzymes, such as those involved in elastin degradation or in the early steps of melanogenesis." (PMID 38910175, 2024). "It is well known that skin aging is related to the destruction of collagen and elastin fibers by metalloproteinases (MMPs)." (PMID 35328415, 2022). "Long-term UVB irradiation has been reported to increase the decomposition of elastin and collagen in skin aging (such as rough skin, suppression of skin elasticity, and skin wrinkles) and/or has a detrimental effect." (PMID 36557596, 2022). "Elastin, collagen-1 and collagen-3 levels are usually decreased in skin aging, leading, among other effects, to the formation of wrinkles, the loss of tensile strength, increased fragility and impaired wound healing." (PMID 34573004, 2021). "The upregulation of MMPs facilitates aging and skin pathologies, by degrading collagen and elastin causing impairments in the extracellular matrix (ECM), thus a reduction of these proteinases is worthful in the context of skin aging." (PMID 33424011, 2021). "UV irradiation-induced skin aging is a heavy extrinsic form of aging resulting in the formation of winkles and a reduction in the levels of collagen and elastin in human skin." (PMID 32825040, 2020). "Characteristic manifestations of skin aging, due to either intrinsic or extrinsic factors, such as ultraviolet (UV) radiation and oxidative stress, include cell senescence, alterations in collagen and elastin networks, and melanogenesis disorders." (PMID 40722928, 2025). "Research has demonstrated that PCs treatments can inhibit oxidative stress in aging skin, increase the collagen and elastin contents within aged dermal layers, mitigate inflammatory responses related to skin aging, and suppress pigmentation changes in aged skin." (PMID 40969599, 2025). "In addition, elastase can hydrolyze the elastin fibers of the skin, leading to skin wrinkling or sagging, and inhibiting the activity of elastase can prevent skin aging." (PMID 36903318, 2023).
skin aging (continued). "In the present study, the increase in elastin and collagen-1 expression with the treatment shows that K. angustifolia could efficiently counter some of the main characteristics of skin aging." (PMID 34573004, 2021). "Indeed, we detected a set of metallo-proteinases (MMP2, MMP14), collagens (e.g. COL6A1, COL3A1, COL5A1 and others) and elastin (ELN), which showed a significant longitudinal change in expression in addition to being closely correlated to skin aging." (PMID 25977295, 2015). "Additionally, in the presence of MAAs, the UV-suppressed genes, procollagen C proteinase enhancer (PCOLCE) and elastin, which are related to skin aging, had increased expression levels equal to those in UV-mock treated cells." (PMID 25317535, 2014). "ROS are a major factor of skin aging, involving damage to DNA, the inflammatory response, reduced production of antioxidants, and the generation of matrix metalloproteinases (MMPs) that degrade collagen and elastin in the dermal skin layer, leading to skin wrinkles and reduced elasticity." (PMID 39070257, 2024). "Therefore, collagen and elastin are important indicators for studying skin aging." (PMID 36364921, 2022). "One of the most prominent manifestations of skin aging is wrinkle formation, which arises from the progressive degradation of key extracellular matrix (ECM) components like collagen and elastin." (PMID 41155313, 2025). "Elastin (ELN) and collagen type I (COL-1) are indicators of skin aging, and malondialdehyde (MDA) and reactive oxygen species (ROS) are indicators for testing whether the organism is peroxidised." (PMID 39480640, 2024). "Additionally, collagen and elastin content, which are the crucial extracellular matrix components involved in skin aging, were not analyzed following the combined RF + TUS application, as it was beyond the scope of this study." (PMID 40243133, 2025). "Therefore, the expression of COL‐1, COL‐3, ELN, and MMP‐1 is closely related to skin aging." (PMID 40012471, 2025). "The results show that equol may be used locally to treat and prevent skin aging by enhancing the ECM component in the skin, specifically by stimulating the production of type I collagen, type III collagen and the protein elastin (ELN) while downregulating MMPs." (PMID 31747092, 2020).
pulmonary fibrosis (33 papers, 2008 to 2026). Chronic progressive interstitial lung disorder characterized by the replacement of the lung tissue by connective tissue, leading to progressive dyspnea, respiratory failure, or right heart failure. "We thus identify TRPML1 as a regulator of MMP release in the lung with loss of TRPML1 resulting in lung fibrosis due to excessive extracellular collagen and elastin accumulation." (PMID 41714729, 2026). "In lung fibrosis models, collagen deposition is observed after 14 days, primarily in peripheral vessels and alveolar walls, with cross-linked elastin indicating developmental relevance." (PMID 40558439, 2025). "While no such biomarker currently exists, we propose the ratio of free to peptide-bound desmosine, a unique crosslink of elastin, as a potential candidate for detecting the earliest modifications in lung microarchitecture associated with pulmonary fibrosis." (PMID 38673771, 2024). "Elastin is critical for elasticity in lung tissue, and degradation by elastase has been implicated in lung fibrosis." (PMID 33088835, 2020). "These proteins form a network that governs ECM stability and late-stage upregulation of COL18A1 and downregulation of ELN, both of which highlight a unique pattern of structural vulnerability to lung fibrosis and reduced elasticity in the aging lung." (PMID 40664891, 2025). "A better understanding of the mechanism of elastin degradation and its significance for the pathology of fibrosis will likely help to identify novel therapeutic targets and prevent pulmonary fibrosis in COVID-19 patients." (PMID 38397474, 2024). "The core elastin protein of elastic fibers, which is responsible for their distensibility, undergoes marked injury and repair in pulmonary fibrosis." (PMID 38673771, 2024). "As we previously reported, HSP90 inhibitors AUY-922 and AT-13383 significantly downregulate the overexpression of collagen, fibronectin and elastin expression in mice with HCl-induced pulmonary fibrosis." (PMID 36419627, 2022). "This study demonstrates that PXS-5505 inhibits activity of lysyl oxidase in the lung, reduces bleomycin-induced increases in collagen, elastin and their cross-links and thereby ameliorates lung fibrosis." (PMID 35628342, 2022). "Idiopathic pulmonary fibrosis is a progressive, chronic lung disease characterized by the accumulation of extracellular matrix proteins, including collagen and elastin." (PMID 33456450, 2020). "Previous studies have also found concurrent increases in TENASCIN-C and elastin, for example in patients with lung fibrosis." (PMID 30995723, 2019). "In this study we used the expression of elastin as a marker of pulmonary fibrosis because excessive elastin deposition characterizes chronic lung disease." (PMID 27581501, 2017). "Pulmonary fibrosis, as indicated by up‐regulation of elastin, collagen‐1, TGF‐β1 and ODC, was attenuated by captopril but not by hydralazine." (PMID 27581501, 2017). "Clinical relevance was assessed by measuring levels of NE-generated elastin fragments in serum of patients diagnosed with idiopathic pulmonary fibrosis (IPF, n = 10) or lung cancer (n = 40)." (PMID 25935650, 2015). "One of the crucial hallmarks of pulmonary fibrosis is the excessive production of extra cellular matrix (ECM) (collagen, fibronectin, elastin, laminin and hyaluronic acid), which is associated with enhanced fibroblasts proliferation and transformation to myofibroblasts." (PMID 35625905, 2022). "Increased elastin gene and collagen 1a1 gene expression in fibrotic lesions have been reported in a bleomycin-induced pulmonary fibrosis model, suggesting that increased elastin as well as collagen was involved in the fibrosis of the lung histopathology findings of CL-PAA." (PMID 36430349, 2022). "Similarly, in the bleomycin-induced mouse lung model, PXS-5505 reduced pulmonary fibrosis toward normal levels, mediated by its ability to normalise collagen/elastin crosslink formation." (PMID 35628342, 2022).
pulmonary fibrosis (continued). "During the development of idiopathic pulmonary fibrosis (IPF), elastin is broken down and replaced with a stiffer substrate which interferes with normal breathing." (PMID 41502559, 2025). "Crosslinking of matrix components, such as collagen and elastin, through the conversion of lysine moieties to aldehydes by the enzyme LOX, reduces matrix proteolysis in skin and lung fibrosis." (PMID 36359382, 2022). "Idiopathic pulmonary fibrosis (IPF) is a progressive, chronic lung disease characterized by the accumulation of extracellular matrix proteins, including collagen and elastin, because of excessive synthesis by lung fibroblasts and myofibroblasts." (PMID 33456450, 2020). "As the PTHrP system attenuates an alveolar lipofibroblast‐to‐myofibroblast transdifferentiation, an initial step of pulmonary fibrosis, we expected that L‐NAME‐induced PTHrP expression will repress elastin expression and therefore pulmonary fibrosis." (PMID 27581501, 2017). "Elastin deposition was observed in pulmonary fibrosis but not within renal fibrosis, suggesting that elastin accumulation is minimal or absent in the early stages of renal fibrosis." (PMID 40558439, 2025). "Regarding pulmonary fibroblasts from patients with idiopathic pulmonary fibrosis, both Hylach and HA significantly reduced the gene and protein expression of collagen III, elastin, and TGF-β, with the effect of Hylach being more pronounced than that of HA (p < 0.0001 vs. p < 0.01)." (PMID 38201803, 2023). "While our in vitro findings in adult Human lung fibroblasts showed that PRRX1 inhibition mainly impacted ACTA2 expression levels, Prrx1 ASO treatment in the bleomycin mouse model of lung fibrosis also inhibited the deposition of ECM proteins such as Collagen 1, Fibronectin, Tenascin C, and Elastin." (PMID 37261432, 2023). "Further investigation is required to establish the relevance of accelerated elastin degradation in IPF and to determine whether decelerating this process leads to slower progression of lung fibrosis and better survival for patients with IPF." (PMID 29558926, 2018). "Markers of mature elastin degradation, mainly desmosine and isodesmosine have been commonly used and found to be present in chronic conditions such as aging, COPD and idiopathic pulmonary fibrosis." (PMID 30170599, 2018). "Pulmonary fibrosis is a major clinical problem characterized by accumulation of extracellular matrix (ECM) proteins, including collagen, fibronectin, proteoglycans, and elastin, leading to abnormal lung architecture and severe impairment of lung function." (PMID 18638383, 2008). "Concerning pulmonary fibrosis, which is the end-stage consequence of various forms of interstitial lung disease (ILD), changes in the structure of arterial layers with significant collagen and elastin deposition in the adventitia was found in patients with idiopathic pulmonary fibrosis (IPF)." (PMID 37582200, 2024). "Increased levels of lysyl oxidase (LOX), an amine oxidase critical for the initiation of collagen and elastin cross-linking, increased mRNA levels of collagen type I (Col1a2), collagen type III (Col3a1) and matrix metalloproteinase (Mmp2) have been reported in murine models of lung fibrosis." (PMID 24204629, 2013). "The diagnostic power of ELN-441 was higher for COPD than IPF, which is in accordance with the recent research in the field of MMPs and elastin in COPD, and that the main pathologic problem in IPF might be pulmonary fibrosis and not elastin degradation." (PMID 22818364, 2012).
chronic obstructive pulmonary disease (31 papers, 2008 to 2026). A chronic and progressive lung disorder characterized by the loss of elasticity of the bronchial tree and the air sacs, destruction of the air sacs wall, thickening of the bronchial wall, and mucous accumulation in the bronchial tree. "MFAP2 is a glycoprotein which is a component of elastin-associated microfibrils, with SNPs in this gene associated with chronic obstructive pulmonary disease and lung function." (PMID 36725857, 2023). "Significant structural and mechanical remodeling of ECM is associated with various diseases, such as the proteolytic digestion of elastin caused by chronic obstructive pulmonary disease (COPD) and the stiffening of bone marrow caused by blood cancer." (PMID 36297985, 2022). "MMP12 is associated with elastin degradation and macrophage migration in various diseases, such as chronic obstructive pulmonary disease, skin diseases and cancers." (PMID 33935718, 2021). "When level of elastase activity is heightened in individuals with α1-antitrypsin deficiency, elastin in the lungs will slowly be degraded, resulting in early-onset of chronic obstructive pulmonary disease (COPD)." (PMID 40087166, 2025). "This shared association suggests that alterations in elastin maintenance may contribute to the development of both chronic obstructive pulmonary disease and inguinal hernia and may be the mechanism through which chronic obstructive pulmonary disease increases the risk of inguinal hernias." (PMID 26686553, 2015). "Histologic investigations demonstrated thickening of the intimal and medial layers, reduction in small arterial numbers, and altered elastin deposition in smokers and individuals with mild to moderate chronic obstructive pulmonary disease (COPD)." (PMID 42088789, 2026). "As a key component of the alveolar architecture, elastin becomes severely dysregulated in chronic obstructive pulmonary disease (COPD), an age-related lung disorder characterized by progressive airflow limitation." (PMID 41281748, 2025). "The cleavage of elastin is linked to the pathophysiology in injury-associated fibrosis, IPF, and chronic obstructive pulmonary disease (COPD)." (PMID 38397474, 2024). "Research has established that the breakdown of elastin is a critical factor in the development of chronic obstructive pulmonary disease." (PMID 37374496, 2023). "Previous studies have found that MMP12-generated elastin fragments act as an autoantigen to drive the autoimmune process in chronic obstructive pulmonary disease (COPD) mouse models." (PMID 37176151, 2023). "In chronic obstructive pulmonary disease (COPD) tissue elastin injury and depletion have been demonstrated in lung parenchyma." (PMID 19243601, 2009). "ZZ serum levels are only 10–15% of normal individuals who bear two healthy M-A1AT alleles, which is not sufficient to protect elastin fibers in the lung from breakdown by NE, resulting in chronic obstructive pulmonary disease (COPD)." (PMID 31097772, 2019). "Systemic alterations to the synthesis and degradation of elastin may be important to our understanding of disease phenotypes in chronic obstructive pulmonary disease." (PMID 31234847, 2019). "Thus, using ELISA from elastin peptides, we verified that 43% of the patients with severe early onset of chronic obstructive pulmonary disease tested positive for IgG to elastin in their serum compared to healthy controls." (PMID 21573156, 2011). "In AAT deficiency disease (AATD), the elastin and collagen of the lung alveoli are not sufficiently protected from neutrophil elastase, a serine protease, which results in progressive destruction of lung parenchyma, emphysema, and chronic obstructive pulmonary disease (COPD)." (PMID 35806409, 2022).
chronic obstructive pulmonary disease (continued). "This imbalance between protease(s) degrading the parenchymal extracellular matrix and their inhibitors is responsible for the destruction of lung elastin and, if it is persistent or recurrent over years, it results in respiratory complications, such as chronic obstructive pulmonary disease (COPD)." (PMID 32887469, 2020). "The generated protease–anti-protease imbalance and the pro-inflammatory environment lead to degradation of elastin and other basal membrane and matrix components in the lung parenchyma, and consequently, development of the chronic obstructive pulmonary disease (COPD) and emphysema." (PMID 31450843, 2019). "Although not typically a primary manifestation of disease, cardiac arrhythmia incidence is increased in populations with heritable thoracic aortic disease caused by fibrillin-1 or TGF-β pathway mutations suggesting there may be a correlation between elastin degradation and cardiac electrophysiology." (PMID 37001705, 2023).